GAST (gastrin)
Diseases named in the same sentence as GAST in open-access papers (continued):
Sharing a sentence is not in itself a finding about the gene and the disease.
Hyperglycemia (6 papers, 2009 to 2023). An increased concentration of glucose in the blood. "However, the possibility of anti-hyperglycemia drugs influencing the response to gastrin treatment should be further investigated." (PMID 31430329, 2019). "However, the elevation could be a result of a disturbed feedback mechanism due to neuropathy in the stomach, vagal neuropathy, an increased quantity of gastrin cells in the stomach, reduced number of somatostatin cells, or hyperglycaemia." (PMID 19243587, 2009). "In vivo reprogramming by administering long-term low-dose gastrin and EGF in hyperglycemia mouse can increase SOX9." (PMID 32118053, 2020). "However, the therapeutic efficacy compares well with a previous study of combination EGF and gastrin that also used a model of syngenic islet transplantation in diabetic NOD mice and observed that the median time to recurrence of hyperglycemia was about 8 weeks." (PMID 21966502, 2011).
hyperplastic polyp (6 papers, 2017 to 2025). A polyp found mainly in the stomach and colon. "Elevated blood gastrin levels are also assumed to cause hyperplastic polyps." (PMID 28660530, 2017). "In the present study, although the difference was not statistically significant, there was a trend suggesting that FGPs were less prevalent in the high gastrin level group, whereas hyperplastic polyps were less prevalent in the low gastrin level group." (PMID 39594206, 2024). "Furthermore, the positive correlation between elevated serum gastrin levels and the growth of hyperplastic polyps in this patient is consistent with a previous report showing that higher gastrin levels increased the risk of hyperplastic polyps in PPI users." (PMID 39712905, 2025).
pancreatic adenocarcinoma (6 papers, 2007 to 2020). "The pro-survival cytoprotective protein clusterin (CLU) is gastrin-responsive in rat pancreatic adenocarcinoma cells, and is involved in the anti-apoptotic effect of gastrin." (PMID 28902909, 2017). "We have previously reported that gastrin treatment of the pancreatic adenocarcinoma cell line AR42J resulted in differentially expressed genes which were annotated to cellular responses such as unfolded protein response (UPR)/ER stress and survival." (PMID 28109268, 2017). "The purpose of the present investigation was to study the expression/co-expression of wild type CCK2R, CCK2i4svR, and gastrin mRNA in human pancreatic adenocarcinoma by means of RT-PCR and DNA sequence analysis of selectively cloned PCR amplicons." (PMID 21504585, 2011). "Here, using an siRNA that specifically targets gastrin, we show that endogenous gastrin plays a role in the survival of cell lines representing gastric, colorectal and pancreatic adenocarcinoma." (PMID 17262081, 2007). "Furthermore, it has been shown that CCK2R mRNA, gastrin mRNA and its corresponding proteins are expressed in human pancreatic adenocarcinoma." (PMID 21504585, 2011). "Gastrin mediates its effect via the cholecystokinin-2 receptor (CCK2R), primarily expressed by enterochromaffin-like (ECL) cells, but also reported to be expressed in cancer like colorectal and pancreatic adenocarcinomas." (PMID 24086717, 2013). "Based on these findings, it was suggested that human pancreatic adenocarcinomas might be stimulated by an autocrine loop involving co-expression of CCK2R and gastrin." (PMID 21504585, 2011). "Our transcriptome analysis of differentially expressed genes in the pancreatic adenocarcinoma AR42J cells revealed that gastrin upregulates the mRNA level of autophagy related genes (e.g. Sqstm1 and beclin 1 (E-MTAB-1268 and GSE32869)), suggesting that gastrin may induce autophagy." (PMID 28109268, 2017).
pancreatic neuroendocrine tumor (6 papers, 2013 to 2025). Pancreatic endocrine tumor, also known as pancreatic neuroendocrine tumor (PNET), describes a group of endocrine tumors originating in the pancreas that are usually indolent and benign, but may have the potential to be malignant. "Gastrin is expressed in the embryonic pancreas and is common in islet cell tumors, but the lineage and regulators of pancreatic gastrin+ cells are not known." (PMID 23940571, 2013). "The second major class of pancreatic cancer is pancreatic neuroendocrine tumors (also termed islet cell tumors), which arise from cells that make up the endocrine gland of the pancreas, which secretes insulin, gastrin, and glucagon into the serum to regulate glucose uptake and metabolism." (PMID 37371782, 2023). "Pancreatic neuroendocrine tumors secreting gastrin and adrenocorticotropic hormone (ACTH) are rare." (PMID 37849614, 2023).
adenoma (5 papers, 2002 to 2022). A neoplasm arising from the epithelium. "In colon carcinogenesis, co-expression of gastrin and its receptor occurs in the early stage in the adenoma-carcinoma sequence." (PMID 32485921, 2020). "Mean serum gastrin-17 concentrations of the adenoma group and EGC group were 10.4 and 9.0 pmol/L, respectively (p = 0.54)." (PMID 28072871, 2017). "Omeprazole and lansoprazole-induced hyper-gastrinaemia (resulting in serum gastrin levels of 34.0 and 153.0 pM, respectively) significantly increased the weight of the human adenoma grafts (43% (P=0.016) and 70% (P=0.014), respectively)." (PMID 12189558, 2002). "This may indicate a shift to a more malignant phenotype in the present adenoma model following exposure to gastrin." (PMID 12189558, 2002). "While the glands at the base of the adenoma showed diffuse staining of MUC6 but no gastrin staining, composed of columnar epithelium with only a small number of main cells scattered, indicating that it was a pseudopyloric gland metaplasia." (PMID 35508985, 2022).
bile reflux (5 papers, 2022 to 2025). "An increase in cholecystokinin may facilitate sphincter relaxation, bile excretion and common bile duct pressure regulation, while an increase in gastrin may relax the pyloric sphincter, exacerbate the bile reflux and cause elevated bile acid levels in the gastric juice." (PMID 37920676, 2023). "H pylori infection may increase gastrin secretion, decreasing peristalsis in the gastric antrum, thereby promoting bile reflux." (PMID 40988192, 2025). "In addition, bile reflux can stimulate gastrin secretion from G cells, which promotes gastric acid secretion and inhibits pyloric sphincter contraction, further promoting bile reflux and forming a vicious circle." (PMID 35379788, 2022).
depression (5 papers, 2025). "Our predictive model demonstrated that depression disorder, drinking consumption, family history of digestive disorders, HP infection, pepsinogen I, pepsinogen II and gastrin 17 were the independent risk factors of CAG with high accuracy and good calibration." (PMID 40612582, 2025). "Our multivariate logistic regression analysis revealed that depression disorder, drinking consumption, family history of digestive disorders, HP infection, pepsinogen I, pepsinogen II and gastrin 17 were the independent risk factors of our predictive model." (PMID 40612582, 2025). "However, a plausible explanation is that PPIs can lead to increased serum gastrin levels, which play a role in regulating and modifying aspects of behavior that can result in depression." (PMID 41551185, 2025). "Moreover, increased gastrin levels can activate cholecystokinin type B receptors in the brain, leading to depression." (PMID 41551185, 2025).
gastric disease (5 papers, 2017 to 2025). "Investigations into the effect of gastrin on gastric disease are important for further understanding of the disease and its treatment." (PMID 39457867, 2024). "Pepsinogen (PG) and gastrin-17 (G-17) are widely used in the screening of gastric diseases." (PMID 41187167, 2025). "In addition, it was reported that seven H. pylori-positive patients (with HtrA-L171 allele) obtained from patients non-ulcer dyspepsia, revealed elevated serum gastrin values compared to eleven patients carrying HtrA-S171 isolates, which could be involved in gastric disease outcome." (PMID 37183214, 2023).
hepatocellular carcinoma (5 papers, 2009 to 2022). A malignant tumor that arises from hepatocytes. "In addition, gastrin and cancer correlation has been demonstrated in gastric, colorectal, and hepatocellular cancers." (PMID 32784492, 2020). "Other hormones that may cause paraneoplastic diarrhea include glucagon (glucagonoma), gastrin (gastrinoma or hepatocellular carcinoma), somatostatin (somatostatinoma or pheochromocytoma), and the prostaglandins (hepatocellular carcinoma)." (PMID 29177551, 2018). "Previous findings in a human study that demonstrated hepatocellular carcinoma and CCA express the CCK-B/gastric receptor and precursor forms of gastrin." (PMID 30018559, 2018).
Hypoglycemia (5 papers, 2018 to 2024). A decreased concentration of glucose in the blood. "PPIs can significantly raise serum gastrin concentration and affect glucose metabolism by promoting B-cell regeneration and expansion; PPIs can therefore increase the risk of hypoglycemia." (PMID 37700268, 2023).
metastatic disease (5 papers, 2003 to 2025). "Of the 18 patients who died of disease or were alive with recurrent or metastatic disease, all but one had a tumor with at least focal positivity for gastrin, and 8 had serotonin reactivity in their tumors." (PMID 40553402, 2025). "Four patients were treated with a somatostatin analog: one patient with a locally recurrent disease, one patient with an extremely high gastrin level of 2893 ng/mL, one patient with a 2.5 cm tumor diameter, and one patient with a metastatic disease." (PMID 36979807, 2023). "In general, gastrin levels are higher in pancreatic than in duodenal NENs, and are proportional to tumor burden and in patients with metastatic disease, exceedingly high gastrin levels may be observed." (PMID 25038902, 2014). "Even if it is difficult to statistically compare these results, they all indicate that PD can effectively control ZES-related gastrin secretion in patients with no metastatic disease." (PMID 33649917, 2021).
polyp (5 papers, 2017 to 2025). A usually exophytic mass attached to the underlying tissue by a broad base or a thin stalk. "Factors such as older age and elevated levels of gastrin and chromogranin A were linked to polyp development." (PMID 39632655, 2024). "Elevated serum gastrin in this context is believed to function as a trophic factor for oxyntic mucosa, further contributing to polyp development." (PMID 40861607, 2025). "Increased gastrin induced by H. pylori infection may contribute to carcinogenesis by cell proliferation in the colon mucosa, and H. pylori itself can act on the colorectal epithelium through inflammatory responses and affect polyp growth or promote mucosal dysplasia." (PMID 28068908, 2017).
somatostatinoma (5 papers, 2015 to 2022). A rare, usually malignant neuroendocrine tumor arizing from delta cells. "In most patients (92.7%), the clinical somatostatinoma syndrome was caused by the inhibition of insulin, glucagon, gastrin, secretin, and somatotrophin." (PMID 33204258, 2020).
glioblastoma (4 papers, 2017 to 2022). The most malignant astrocytic tumor (WHO grade IV). "Other cancers, such as glioblastoma, can also be affected by gastrin by promoting angiogenesis." (PMID 34349170, 2021).
Hypertension (4 papers, 2017 to 2025). The presence of chronic increased pressure in the systemic arterial system. "Our findings indicate that the elevation of gastrin might be the underlying mechanism of salt-induced hypertension, which sheds some new light on prevention and a possible therapeutic target for hypertension in the future." (PMID 28420122, 2017). "The gavage of gastrin-SiO2 microspheres mitigated the high-salt diet-induced hypertension in Dahl salt-sensitive rats with a decrease in intestinal NHE3 expression and activity, increase in stool sodium." (PMID 35674015, 2022). "Gastrin-SiO2 microspheres treatment prevented the high salt-induced hypertension and increase in urine Na concentration by inhibiting intestinal Na+/H+ exchanger 3 trafficking and activity, increasing stool sodium without inducing diarrhea." (PMID 35674015, 2022). "Genome-wide association studies showed that the chromosomal loci of gastrin and CCKBR were linked to hypertension." (PMID 28420122, 2017). "Determining the molecular mechanism and signaling molecules responsible for the effects of gastrin on salt sensitivity and hypertension could be of great interest." (PMID 28420122, 2017). "Indeed, D1-like receptors, such as D1 dopamine receptor, and CCKBR synergistically increase sodium excretion in normotensive but not in spontaneously hypertensive rats, suggesting that the dysregulation of interaction between gastrin and CCKBR may be a mechanism in hypertension progress." (PMID 28420122, 2017).
Insulin resistance (4 papers, 2023 to 2025). Increased resistance towards insulin, that is, diminished effectiveness of insulin in reducing blood glucose levels. "Postoperatively, many of these patients develop insulin resistance, which hampers the secretion and release of gastrin and disrupts the function of the autonomic nervous system, thereby impairing gastric emptying." (PMID 39835113, 2024). "Hence, even though the GAST+ cells produced by insulin resistance in mice or the MAFBKO GAST+ β-like cells have some molecular similarities to stomach G cells, these conditions alone are insufficient to completely reprogram the β cell toward a de facto G cell." (PMID 37606041, 2023). "As a result, we predict that these associated gene signatures will be induced even earlier than GAST itself upon pathologically induced loss of MafA or MAFB, which could be tested temporally in future studies in models of insulin resistance (i.e., following S961 or high-fat diet treatment)." (PMID 37606041, 2023).
lymph node metastasis (4 papers, 2012 to 2025). "Although the serum gastrin levels were not statistically different between the TNM stages of our patient cohort, our data found that serum gastrin levels were significantly higher in patients with lymph node metastasis." (PMID 22719803, 2012). "However, we did show that there was a statistically significant increase of serum gastrin in patients with lymph node metastases." (PMID 22719803, 2012). "Moreover, tumour tissue investigation may need, other than Ki‐67, hormonal immunohistochemical characterisation since different functional types (such as gastrin‐producing or somatostatin‐producing or ordinary non‐functioning types) may have different risks of lymph node metastases." (PMID 40524475, 2025). "Patients with lymph node metastasis had higher serum gastrin levels than patients without metastasis and this difference was statistically significant." (PMID 22719803, 2012).
myocardial infarction (4 papers, 2021 to 2025). Gross necrosis of the myocardium, as a result of interruption of the blood supply to the area, as in coronary thrombosis. "We demonstrated that increased plasma gastrin level played a protective role against cardiac dysfunction after myocardial infarction." (PMID 34412590, 2021). "A previous study reported that the serum concentration of gastrin was significantly increased after myocardial infarction." (PMID 34412590, 2021). "It is known that increased gastrin concentration is negatively correlated with cardiovascular mortality, and plasma gastrin levels are increased in patients after myocardial infarction (MI)." (PMID 34412590, 2021). "Therefore, it is possible that gastrin may exert a protective effect against myocardial infarction." (PMID 34412590, 2021).
osteoporosis (4 papers, 2023 to 2026). A condition of reduced bone mass, with decreased cortical thickness and a decrease in the number and size of the trabeculae of cancellous bone (but normal chemical composition), resulting in increased fracture incidence. "Long-term PPI use has been linked to osteoporosis and osteoporotic fractures, with suggested mechanisms including calcium/B12 malabsorption, gastrin-induced parathyroid hyperplasia, and osteoclastic vacuolar proton pump inhibition." (PMID 41010960, 2025). "Long-term PPI use has been linked with osteoporosis and increased fracture risk, with suggested mechanisms including calcium/B12 malabsorption, gastrin-induced parathyroid hyperplasia, and direct inhibition of osteoclastic vacuolar proton pumps." (PMID 41010960, 2025). "Two main mechanisms were described for osteoporosis induced by PPIs, gastrin over-secretion, and hypochlorhydria." (PMID 38234669, 2024). "Considering PPIs' inhibitory effect on gastrin production and the fact that hypergastrinemia is a major cause of PPI-induced bone loss, long-term usage of pump inhibitors can lead to osteoporosis." (PMID 37711876, 2023). "Hence, it was hypothesized that gastrin and PTH played a key role in osteoporosis because adding octreotide to correct hypergastrinemia in the rats consuming pantoprazole caused no significant changes in the number of osteoclasts and osteoblasts compared to the controls." (PMID 37711876, 2023).
Barrett’s esophagus (3 papers, 2014 to 2024). Esophageal lesion lined with columnar metaplastic epithelium which is flat or villiform. "A biological mechanism that can explain the finding of a risk reduction of oesophageal adenocarcinoma after discontinuation of PPI therapy is normalization of the elevated gastrin levels associated with long-term PPI use." (PMID 36258093, 2022). "COX-2, a pro-inflammatory enzyme, promotes esophageal adenocarcinoma; normal gastrin levels may mitigate esophageal cancer risk by counteracting COX-2 activity, while elevated gastrin levels may upregulate COX-2 expression." (PMID 39749203, 2024). "A potential causal effect of gastrin on neoplastic progression in human Barrett’s esophagus (BE) has been supported by a study showing that serum gastrin levels were significantly correlated with cellular proliferation in nondysplastic BE patients on PPI therapy." (PMID 25415190, 2014). "The biological mechanism by which long-term PPI use may lead to esophageal adenocarcinoma is related to its effect on gastrin levels." (PMID 39749203, 2024). "Thus, normalized gastrin levels may counteract COX-2 activity and decrease oesophageal adenocarcinoma risk, explaining why PPI discontinuation could prevent this tumor." (PMID 36258093, 2022). "Gastrin upregulates oesophageal expression of the pro-inflammatory enzyme COX-2, which is considered a promotor of oesophageal adenocarcinoma development." (PMID 36258093, 2022).
carcinoid tumour (3 papers, 1988 to 2009). "In the present study, we employ transcript profiling to examine molecular mechanisms underlying proliferative responses in BON carcinoid tumour cells after exposure to gastrin, HGF, EGF and PACAP." (PMID 15846300, 2005). "First, there are reasons to believe that gastrin plays a role as a regulator of carcinoid tumour growth in vivo." (PMID 15846300, 2005). "Since gastrin appears to be an important growth factor of various tumour cell types, and since some gastric carcinoids have been shown to express the CCK2 receptor, we examined whether gastrin could affect growth of carcinoid tumour cells as well." (PMID 15846300, 2005). "Together, our findings support the view that gastrin may act as a regulator of carcinoid tumour growth." (PMID 15846300, 2005).
cardiac hypertrophy (3 papers, 2021 to 2022). "Genes coexpressed with PER3 were correlated with “Development_Gastrin in cell growth and proliferation”, “NF-AT signaling in cardiac hypertrophy”, and “Immune response_Gastrin in inflammatory response”." (PMID 36385012, 2022).
duodenogastric reflux (3 papers, 1993 to 2024). Retrograde flow of duodenal contents (bile acids; pancreatic juice) into the stomach. "Gastric distension caused by duodenogastric reflux and the passage of alkaline duodenal fluid into the stomach are the primary factors responsible for enhanced gastrin secretion." (PMID 38672331, 2024). "Complete duodenogastric reflux has similar effects on the pancreas but the gut peptide involved is gastrin." (PMID 8494719, 1993).